FOXM1 (forkhead box M1)
Diseases named in the same sentence as FOXM1 in open-access papers (continued):
Sharing a sentence is not in itself a finding about the gene and the disease.
hepatocellular carcinoma (continued). "For example, MYCNOS, which is upregulated in hepatocellular carcinoma cells and tissues, affects disease progression, shortens patient survival and acts as an endogenous sponge of miR-216b, thereby regulating the expression of FOXM1 and promoting the proliferation of glioblastoma cells." (PMID 38895621, 2024). "In addition, the FOXM1/UBE2S/PTEN/p/AKT axis it participates in may become a potential therapeutic direction for hepatocellular carcinoma." (PMID 38312603, 2024). "The transcriptional activator Forkhead box M1 (FOXM1) has been shown to increase KIF4A expression in hepatocellular carcinoma (HCC)." (PMID 35312737, 2022). "Moreover, knockdown of HMGCR reduced FOXM1 expression in hepatocellular carcinoma." (PMID 36564758, 2022). "The Forkhead Box (Fox) m1b (FOXM1) transcription factor, which is required for hepatocellular carcinoma (HCC) development, comprises an inhibitory ARF target." (PMID 33445626, 2021). "Additionally, USP39 regulates the growth of hepatocellular carcinoma via Forkhead box M1 (FoxM1)." (PMID 30898977, 2019). "In addition, forced expression of FoxM1 restored statins-mediated cell death of human hepatoma cells, indicating that cell death in the mevalonate pathway might be regulated through FoxM1." (PMID 29765517, 2018). "From the previous report, TNF-α could induce the upregulation of FoxM1 in hepatocellular cancers." (PMID 29554906, 2018). "In vivo, co-culturing poorly invasive hepatoma cells with exosomes from highly invasive cells increased tumor volumes, upregulated lncRNA-PVT1, FoxM1, Ki67, and MMP9 expression, and downregulated miR-345-5p expression." (PMID 40486884, 2025). "For example, the transcription factor FOXM1 can directly promote the transcription of TYMS, which can lead to the resistance of hepatocellular carcinoma cells to chemotherapeutic agents such as 5-FU." (PMID 39353904, 2024). "Indeed, the combination of a FOXM1 inhibitor with an anti-VEGFR2 monoclonal antibody improved tumor control compared to a single agent in hepatocellular carcinoma (HCC) tumor xenografts and provided a novel approach for the treatment of advanced HCC." (PMID 38398147, 2024). "In hepatocellular carcinoma, Xiang and colleagues demonstrated the cancer-inhibitory activity of PINT87aa embedded in lncRNA LINC-PINT depending on its suppression of FOXM1-mediated PHB2." (PMID 38351332, 2024). "In this comprehensive study, we embarked on an innovative exploration into the realm of hepatocellular carcinoma (HCC), focusing on the potential prognostic implications of FOXM1 gene expression and its non-invasive prediction using dual-region CT radiomics technology." (PMID 37817774, 2023). "High expression of GUSBP11 in renal cancer is associated with a smaller tumor size and absence of metastasis, and SLC2A1-AS1 inhibits hepatocellular carcinoma progression and glycolysis through the STAT3/FOXM1/GLUT1 axis." (PMID 37020128, 2023). "Relevant to MPNST, a tumor initiated by Ras hyperactivation, FOXM1 is required for growth in other RAS-driven tumors, such as hepatocellular carcinoma, colorectal cancer, and pancreatic ductal adenocarcinoma." (PMID 37686402, 2023). "In a transgenic mouse model of hepatocellular carcinoma driven by constitutively active YAP (YAPS127A), inhibition of FOXM1 with thiostrepton blocked the YAP-induced chromosomal instability phenotype." (PMID 37686402, 2023). "FOXM1 had a positive correlation with mevalonate pathway-related genes including HMGCR and SREBP2 in patients with hepatocellular carcinoma." (PMID 36564758, 2022). "The result showed that FoxM1 and STMN1 highly express in almost all types of solid tumors in a serial of independent cohorts, including gastric cancer, hepatocellular carcinoma and colorectal cancer." (PMID 33526768, 2021). "The expression level of linc-ROR was elevated in hepatocellular carcinoma, and the sponge action of linc-ROR on miR-876-5p released FOXM1, thus forming a positive feedback loop." (PMID 33163123, 2020).
hepatocellular carcinoma (continued). "The protein level of alpha smooth muscle (α-SMA) was reduced and several hepatocellular carcinoma-related genes such as MMP9, FoxM1 were down-regulated." (PMID 32471201, 2020). "FOXM1 is also regulated by another stress signaling pathway, TNFα/ROS/HIF-1 in hepatocellular carcinoma." (PMID 33680951, 2020). "The DNA-binding protein, CTCF, may regulate the motility and invasiveness of primary hepatocellular carcinoma (HCC) cells via interaction with the CTCF-binding site(s) located in the proximal promoter of FOXM1." (PMID 30208972, 2018). "Increasing evidence suggests that FOXM1 expression is substantially elevated in most human malignancies, such as glioblastoma, lung cancer, hepatocellular carcinoma (HCC), breast cancer, and pancreatic cancer, and plays a crucial role in tumorigenesis, angiogenesis, invasion, and metastasis." (PMID 24325450, 2013). "In hepatocellular carcinoma (HCC) and cholangiocarcinoma (CCA), MAT1A expression is reduced, and the induction of FOXM1 and NF-κB expression is accompanied by a decrease in MATα1 (the protein encoded by MAT1A) expression, while MATα1 positively regulates the expression of p50 and p65." (PMID 41513616, 2026). "Additionally, the activation of H3K4me3 was found to be necessary for the UBE2S promoter to bind to FOXM1 and activate UBE2S transcription in hepatocellular carcinoma, thereby increasing resistance to oxaliplatin and 5-FU." (PMID 38312603, 2024). "The activation of glioma-associated oncogene family zinc finger 2 (Gli2), a central figure in Hedgehog (Hh) signaling pivotal for hepatocellular carcinoma (HCC) development, has been found to indirectly stimulate the expression of KIF20A through the activation of FOXM1." (PMID 39272816, 2024). "Interestingly, FOXM1 physically interacts with YAP/TEAD complexes in sarcoma and hepatocellular carcinoma to alter the transcription of genes necessary for promoting proliferation and blocking apoptosis." (PMID 37686402, 2023). "A PubMed search with the keywords ‘radiomics’, ‘liver cancer’ or ‘hepatocellular carcinoma’, and ‘FOXM1’ yielded no pertinent studies, underscoring the groundbreaking nature of our research endeavor." (PMID 37817774, 2023). "Abnormal upregulation of FOXM1 is related to the development of the majority of human cancers, such as bladder cancer, NSCLC, colorectal cancer, cervical cancer, and hepatocellular carcinoma." (PMID 35756697, 2022). "Since LECT2 was reported to antagonize MET receptor activation in hepatocellular carcinoma and non-small cell lung cancer, we speculated that LECT2 might regulate FOXM1 signaling by targeting MET." (PMID 33937262, 2021). "In addition, HBx up-regulated Forkhead box M1 (FoxM1) expression through ERK/CREB signaling pathway, contributing to invasion and metastasis of hepatoma cells." (PMID 34456908, 2021). "miR-34a efficiently targeted Forkhead Box M1(FOXM1) and c-Myc in hepatocellular carcinoma." (PMID 29614790, 2018). "FoxM1 was highly expressed in Hepa1-6 hepatoma cell lines regarded as target cells (data not shown)." (PMID 27351282, 2016). "Furthermore, forkhead box M1 (FOXM1)-activated IGF2BP3 enhances ribonucleotide reductase M2 (RRM2) mRNA stability in an m6A-dependent manner, inhibiting ferroptosis and promoting M2 polarization in hepatocellular carcinoma." (PMID 41376856, 2026). "For instance, forkhead box protein M1 (FOXM1) activates CCNB1, triggering accelerated hepatocellular carcinoma (HCC) cell proliferation." (PMID 41614789, 2025). "These CIN signatures were detected in hepatocellular carcinoma (HCC), and YAP in cooperation with forkhead box M1 (FOXM1) was identified as a driver of CIN gene expression in HCC." (PMID 29464042, 2018). "However, in instances where FOXM1 was tested as the main tumor inducer (i.e., without a second tumor induction stimulus or oncogene), FOXM1b overexpression alone was insufficient to generate hepatocellular carcinoma and lung adenocarcinoma." (PMID 34205406, 2021).
hepatocellular carcinoma (continued). "In hepatocellular carcinoma (HCC) cell models, CCAT2 was reported to promote cellular migration, proliferation, and decreased apoptosis by interaction with another member of the FOX gene family, FOXM1." (PMID 34830370, 2021). "Additionally, the FOXM1/RB1/DNMT3B transcriptional regulatory complex can suppress the expression of FOXO1, resulting in decreased levels of FOXO1 target p16, p21, and p27 in hepatocellular carcinoma (HCC)." (PMID 38672640, 2024).
glioma (156 papers, 2011 to 2026). A benign or malignant brain and spinal cord tumor that arises from glial cells (astrocytes, oligodendrocytes, ependymal cells). "In glioma tumor-initiating cells (TICs), FOXM1 is a critical factor implicated in the proliferation and self-renewal of cancer cells." (PMID 37821870, 2023). "Like many other transcription factors, FOXM1 is strongly associated with the processes related to DNA repair, making glioma cells resistant to chemotherapy as well." (PMID 37821870, 2023). "Not only FOXM1 but also its targets also have been shown to be implicated in the radioresistance of gliomas." (PMID 37821870, 2023). "A study investigating the chemotherapeutic role of Bortezomib and its underlying mechanism in gliomas, revealed a connection between the effect of the proteasome inhibitor and the Akt/FoxM1 signaling axis." (PMID 35409080, 2022). "FoxM1 is also highly expressed in glioblastoma (GBM), and higher FoxM1 expression is associated with worse overall survival in glioma patients." (PMID 32667745, 2020). "Using gain- and loss-of-function studies, we showed that FoxM1/ADAM17 axis promoted the MES transition in glioma cells." (PMID 29700308, 2018). "MYBL2 and FoxM1 expression are significantly associated with clinical stages and overall survival of glioma patients." (PMID 28784180, 2017). "We also demonstrated the existence of a significant association between MYBL2 and FoxM1 expression in glioma." (PMID 28784180, 2017). "To further confirm the association of MYBL2 and FoxM1 with glioma risk, we analyzed the gene expression data of glioma cases in the high-grade glioma (HGG) TCGA data set, which includes 567 glioma tissues and 10 non-tumor tissues." (PMID 28784180, 2017). "In the present study, for the first time, we found that MYBL2 and FoxM1 are significantly associated with glioma progress; meanwhile, MYBL2 is interacted with radiotherapy for glioma survival." (PMID 28784180, 2017). "And, the role of MYBL2 and FoxM1 in glioma cell progression and the underlying mechanisms were studied by using small interfering RNA (si-RNA) and pcDNA3.1 + HAvectors." (PMID 28784180, 2017). "The correlation between MELK expression and FOXM1 expression in AML patients is consistent with the previously reported association between the two proteins in glioma cells." (PMID 25365263, 2014). "Also, the observation with the R15A mutation confirms the regulatory effect of FoxM1 on mitochondrial fusion and fission proteins in glioma cells." (PMID 41323781, 2025). "MYBL2 induction by AKT/FOXM1 signaling was associated with glioma progression and anti-apoptotic mechanisms; however, the AKT inhibitor MK-2206 strongly suppressed MYBL2 in U251 glioma cells and can be a useful drug to tackle the anti-apoptotic mechanisms in glioma based on the AKT-FOXM-MYBL2 axis." (PMID 38835346, 2024). "Because inhibition of UBE2C promotes autophagic cell death in glioma cells, the FOXM1/UBE2C axis could be essential in developing resistance to therapies, and its targeting holds therapeutic value." (PMID 39594778, 2024). "Moreover, it has been shown that higher expression of FoxM1 was associated with poor prognosis and radio resistance in glioma patient." (PMID 28784180, 2017). "However, the high dependence on the FOXM1–Survivin axis may make glioma cells very susceptible to agents specifically targeted to this oncogenic axis, such as bortezomib." (PMID 31796105, 2019). "However, while these findings further emphasise a core role for cell cycle-associated FOXM1 target genes in cancer progression, other studies in gliomas have implicated FOXM1 in promoting the nuclear translocation of β-catenin, resulting in activation of a programme of Wnt target genes." (PMID 25889361, 2015). "FOXM1 expression in human glioma tissue correlates with tumor grade and correlates inversely with patient survival." (PMID 41141395, 2026).
glioma (continued). "We previously reported that FOXM1 functioned as a downstream component of Wnt signaling and played a crucial role in β-catenin's transcriptional activity in glioma cells." (PMID 41141395, 2026). "The observations with the R15 mutant revealed characteristics reminiscent of an auto-inhibited state of FoxM1, suggesting that R15 is indeed important for FoM1 function in glioma cells." (PMID 41323781, 2025). "Reduced m6 A levels in ADAM19 mRNA and in FOXM1 promote glioma stem cell proliferation and self‐renewal and ultimately lead to tumorigenesis." (PMID 40382536, 2025). "AVIL overexpression promotes glioma cell proliferation and migration by regulating FOXM1 and LIN28B." (PMID 39964147, 2025). "Together, our findings suggest that R15 is a critical residue for FoxM1 activity and function in glioma cells." (PMID 41323781, 2025). "Taken together, these findings confirm that FoxM1 is a positive regulator of TFAM expression and R15 site is critical for FoxM1 activity in regulating TFAM expression in glioma cells." (PMID 41323781, 2025). "Our study confirmed that FoxM1 promotes c-Myc and Cyclin D1 expression and is localize in the nucleus as well as the cytoplasm in glioma cells." (PMID 41323781, 2025). "Through the analysis of these mutants, we determined the contribution of each residue to FoxM1 transcriptional activation and function in glioma cells." (PMID 41323781, 2025). "In the present study, we utilized site-directed mutagenesis to investigate the contribution of FoxM1 N-terminal arginine on FoxM1 transcriptional activity and function in glioma cells." (PMID 41323781, 2025). "FoxM1 contributed to glioma progression and malignancy by being involved in cell proliferation, angiogenesis, invasion and maintenance of cancer cell stemness." (PMID 38398118, 2024). "A trial using a polypeptide vaccine targeting LY6K, DEPDC1, KIF20A, and FOXM1 in patients with high-grade glioma showed that the vaccine was well tolerated, elicited an effective immune response, and prevented disease progression for at least 6 months." (PMID 39727968, 2024). "Since FOXM1 is involved in cell cycle regulation and DNA repair, it plays a significant role in driving transcriptional response against radiation in high-grade gliomas." (PMID 37821870, 2023). "A recent clinical trial has highlighted the efficacy of early treatment with a vaccine-based immunotherapy approach using glioma oncoantigens (GOAs) containing FOXM1 before starting chemotherapy or radiotherapy to prevent possible chemo-radio resistance." (PMID 37821870, 2023). "CircCCDC66 promotes glioma proliferation by acting as a ceRNA for miR-320a to regulate FOXM1 expression." (PMID 38098508, 2023). "In higher-grade gliomas, including anaplastic astrocytoma and glioblastoma, the expression of FOXM1 is significantly elevated, resulting in tumor recurrence." (PMID 37821870, 2023). "FOXM1 interacts with β-catenin and contributes to further β-catenin nuclear localization in glioma tumorigenesis." (PMID 37202772, 2023). "Bortezomib is a PI that has shown TMZ-sensitizing properties via inhibiting FOXM1 in both cellular and pre-clinical models for the treatment of high-grade gliomas." (PMID 37821870, 2023). "In glioma, FOXM1 interacts with critical signaling pathways and molecules, including MELK, STAT proteins, Wnt/β-Catenin, growth factors, and non-coding RNAs." (PMID 37821870, 2023). "Accumulating data indicates that FOXM1 acts as an oncogene in various types of cancers, and a significant part of studies has investigated its function in glioma." (PMID 37821870, 2023). "More importantly, overexpression of FOXM1 has been strongly associated with increased proliferation, migration, angiogenesis, invasion, and resistance to radiation and TMZ in glioma through facilitating DNA repair response." (PMID 37821870, 2023). "Various FOXM1 inhibitors have been found in gliomas with chemosensitizing effects on in vivo and in vitro models." (PMID 37821870, 2023).